CRP (C-reactive protein)
Diseases named in the same sentence as CRP in open-access papers (continued):
Sharing a sentence is not in itself a finding about the gene and the disease.
iron deficiency (228 papers, 2005 to 2026). "Due to potential functional iron deficiency, a graded iron supplementation strategy is recommended, accompanied by comprehensive assessment of CRP and iron metabolism indicators, avoiding decisions based solely on single ferritin thresholds." (PMID 41266138, 2025). "Only 17.2% of anemic cases had absolute iron deficiency, while 34.7% had high CRP—highlighting the limitation of hemoglobin as a standalone metric." (PMID 41458907, 2025). "Other clinical tests, such as serum ferritin, transferrin saturation, soluble transferrin receptor, or C-reactive protein, proved to be useful adjunctive tests to assist in the diagnosis of iron deficiency." (PMID 40704327, 2025). "Childhood obesity and overweight were associated with iron deficiency, elevated levels of CRP and glycated hemoglobin, and early cognitive decline linked to both iron deficiency and inflammatory factors." (PMID 41465437, 2025). "The IL-6/CRP inflammatory axis stimulates hepatic hepcidin production, leading to functional iron deficiency, impaired erythropoiesis, and increased red cell anisocytosis, which raises RDW." (PMID 41231809, 2025). "Iron deficiency (ID) in children: determine ferritin (SF) [1B] and possibly CRP (or another inflammatory marker) levels [2C]." (PMID 39519457, 2024). "Infants with iron deficiency were less likely to have infection based on the CRP level, while infants with VAD were five times more likely to have infection." (PMID 39149555, 2024). "In this study, we classified iron deficiency based on serum ferritin levels adjusting for inflammatory markers (CRP)." (PMID 37020182, 2023). "A total of 15.9% had iron deficiency (ID) determined by low ferritin concentration; 16.2% presented biochemical data indicating the presence of an inflammatory process (elevated CRP and/or AGP)." (PMID 36675141, 2023). "Use serum ferritin, CRP, transferrin saturation and serum iron to assess presence of iron deficiency and haemoglobin, blood count and other micronutrients when diagnosing iron deficiency anaemia." (PMID 35735908, 2023). "Laboratory investigations were notable for CRP of 188 mg/L and Hb of 64 g/L with associated iron deficiency." (PMID 37349797, 2023). "Iron deficiency anemia indicates Hb<11g/dL and serum ferritin<15ug/L or ferritin<30ug/L if C-reactive protein>5mg/L24." (PMID 38343768, 2023). "Iron-deficiency is determined by measuring levels of serum ferritin and setting thresholds at ferritin<15ug/L or ferritin<30ug/L if C-reactive protein>5mg/L." (PMID 38343768, 2023). "We have previously reported the relationship between magnesium deficiency and the elevation of inflammatory mediators, specifically CRP." (PMID 37376511, 2023). "In chronic diseases associated with magnesium deficiency, the most commonly used inflammatory marker is CRP." (PMID 36837480, 2023). "Magnesium deficiency has been shown to be accompanied by high CRP in individuals whose magnesium dietary intakes are below the RDA." (PMID 36837480, 2023). "In contrast, the combined use of s-albumin ≥ 3.8 g/dL and s-CRP < 1 mg/dL was shown to significantly decrease the risk of nutritional disorders by multivariate logistic regression analysis in our study." (PMID 38140295, 2023). "Both sTfR and standard parameters of iron deficiency correlated significantly with inflammatory markers (CRP, ESR) and RA activity index (DAS 28)." (PMID 36275413, 2022). "The measurement of CRP is recommended to adjust ferritin cut-off levels to determine iron deficiency." (PMID 38463717, 2022). "Patients with CKD who have high CRP levels is associated with increased risk of developing functional iron deficiency." (PMID 36910371, 2022). "The biomarkers conventionally used for suspected CD are decreased hemoglobin (Hb) due to iron deficiency, elevated C-reactive protein (CRP), erythrocyte sedimentation rate (ESR) and lowered plasma albumin (Alb)." (PMID 35956250, 2022).
iron deficiency (continued). "Infants with iron deficiency were less likely (OR: 0.40; 95% CI: 0.1, 0.7; P = 0.001) to have infection based on CRP and AGP, while infants with VA deficiency were five times more likely (OR: 5.06; 95% CI: 3.2, 7.1; P = 0.0001) to have infection." (PMID 36211493, 2022). "When comparing the groups of patients with and without iron deficiency, significantly higher fatigue levels were observed in patients with iron deficiency, lower Hb levels, and higher CRP levels." (PMID 36140459, 2022). "Although low ferritin is typically used as a marker of iron deficiency, an increased ferritin level is highly associated with elevated C-reactive protein (CRP) levels and chronic inflammation." (PMID 36235680, 2022). "As compared to the Dutch reference group, most ethnic backgrounds were associated with increased odds for iron deficiency after adjusting for age, gestational age at blood sampling and CRP." (PMID 35720171, 2022). "As further measures, this study used standardized Mediterranean anthropomorphic data and BIA-derived measurements together with nutritional-inflammatory markers such as s-albumin, and s-CRP as recognized risk indicators for nutritional disorders in ACKD." (PMID 36079906, 2022). "Nutritional factors such as TBW, ECM, and s-CRP increased the likelihood of nutritional risk while independent predictors such as MM, PA, and s-albumin were shown to diminish the risk of nutritional disorders in ACKD." (PMID 36079906, 2022). "In this scenario, the evaluation of iron deficiency depends on the simultaneous measurement of ferritin and other important inflammatory markers, such as high-sensitivity C-reactive protein (hs-CRP), alpha-1-acid glycoprotein, and TNF-alpha." (PMID 34578841, 2021). "Additional tests such as serum ferritin, transferrin saturation, erythrocyte protoporphyrin, and C-reactive protein (CRP) are required to detect iron deficiency." (PMID 34496786, 2021). "RDW is, however, a powerful independent predictor of health outcomes in risk prediction models that have adjusted for demographics, cardiometabolic risk factors, C-reactive protein, folate, vitamin B12, hemoglobin, iron deficiency, and other factors." (PMID 34959959, 2021). "The iron deficiency subgroup has also a significantly elevated concentration of APPs (CRP and IL-6), ALP activity as well as total and LDL-cholesterol levels." (PMID 34728695, 2021). "As proposed from the literature, elevated inflammatory markers such as C-reactive protein and iron deficiency markers such as iron saturation, low ferritin and low serum iron concentration are related to reactive thrombocytosis." (PMID 34945099, 2021). "The iron deficiency subgroup also had a significantly higher concentration of APPs (CRP and IL-6), ALP activity, and total and LDL-cholesterol levels." (PMID 34680053, 2021). "According to USPSTF review, there is a lack of data evaluating the sensitivity and specificity of other single tests for the detection of iron deficiency, such as serum ferritin, transferrin saturation, erythrocyte protoporphyrin, and CRP." (PMID 34496786, 2021). "When applying this cut-off value to the women in this study who presented with inflammation (elevated CRP), 74.1% (20/27) suffered from iron deficiency." (PMID 33101717, 2020). "Biochemical iron deficiency, iron overload, and vitamin A deficiency were observed only in n = 12, 4, and 2 samples, respectively, and elevated CRP and AGP concentrations were observed in 11 and 7% of samples, respectively." (PMID 32456038, 2020). "The estimated prevalence of iron deficiency in Kisumu increased from 52.8% (all women) to 65.4% (excluding cases with Plasmodium infection, with adjustment for CRP and AGP), whilst the prevalence estimate in Nairobi increased from 29.9% to 33.9%." (PMID 30781529, 2019).
iron deficiency (continued). "Compared with the unadjusted prevalence, the IRC approach resulted in increased estimates of the prevalence of iron deficiency, with highest estimates obtained when ferritin concentrations were adjusted for CRP and AGP." (PMID 30781529, 2019). "Using AGP, on its own or in combination with CRP, led to higher prevalence estimates of iron deficiency." (PMID 30781529, 2019). "The estimated prevalence of iron deficiency in Kisumu increased from 52.8% (all women) to 69.5% (excluding cases with Plasmodium infection, with adjustment for CRP and AGP), whilst the prevalence estimate in Nairobi increased from 29.9% to 41.5%." (PMID 30781529, 2019). "Iron deficiency was confirmed 7/8 (87.5%) students; one student had a normal plasma ferritin and a raised CRP." (PMID 31448286, 2019). "In the 14 students with β-thalassaemia trait and raised ZPP, plasma CRP was normal in 12/14 (85.7%) and ferritin in 13/14 (92.9%); only one student had iron deficiency." (PMID 31448286, 2019). "The prevalence of clinical iron deficiency after adjusting for inflammation/infection based on serum CRP and AGP levels was low (8.7%; SF <15 μg/L), but 41% had marginal iron stores(SF <50 μg/L)." (PMID 31754277, 2019). "Rates of iron deficiency (ferritin <15 μg/L) increased significantly in both groups to ~70% by late pregnancy, while hepcidin, CRP, and AGP concentrations decreased significantly." (PMID 30669280, 2019). "The objective of this study was to evaluate the possible relationship between H. pylori infection and iron deficiency by levels of hepcidin in school-age children, controlling for positive acute-phase proteins, including CRP and AGP." (PMID 31500264, 2019). "The iron deficiency prevalence estimate increased from 53% to 87% in rural Kisumu study and from 30% to 41% in the urban Nairobi study after adjusting for inflammation (CRP and AGP) using the BRINDA internal regression method." (PMID 30781529, 2019). "In 118/1,240 (9.5%) students with a normal hemoglobin genotype and raised ZPP, all had normal plasma CRP (<5 mg/L) and low plasma ferritin concentrations (<15 ng/ml), confirming iron deficiency." (PMID 31448286, 2019). "In women of reproductive age, the incidence of iron deficiency (based on a serum ferritin threshold of 15 μg/L) was 6.1% and 29.0%, respectively, in the subgroups with the highest and lowest deciles of CRP." (PMID 29744352, 2018). "Statistically significant covariates associated with an increased odds of iron deficiency included younger age, higher zBMI, longer total breastfeeding duration, lower meat and meat-alternatives consumption, and lower CRP." (PMID 30249193, 2018). "We demonstrated that the associations between iron deficiency and malaria infection were confounded by the presence of an acute phase response (raised CRP)." (PMID 30231938, 2018). "When potentially misclassified women were excluded (women with raised CRP and ferritin > 15), the prevalence of iron deficiency was 85%." (PMID 30231938, 2018). "The study sample had a mean age of 81 months (standard deviation/SD = 6.6), a mean BLL of 4.2 μg/dL (SD = 2.1), and 41.7% presented iron deficiency, defined as CRP-adjusted serum ferritin below 15 ng/mL." (PMID 30518085, 2018). "The authors proposed that corrections should be applied for CRP or AGP levels during iron deficiency surveillance programs." (PMID 29744352, 2018). "Researchers found that the observed rate of iron deficiency showed a clear inverse relation to CRP levels." (PMID 29744352, 2018). "Prevalence of iron deficiency remained very similar by trial arm using varying CRP cut-offs (5–25 μg/mL)." (PMID 29166928, 2017). "To further assess iron status, we classified our participants using two different definitions of iron deficiency: 1) ferritin < 12 ng/ml or ferritin 12–30 ng/ml and CRP > 5 mg/l; and 2) hepcidin < 2.5 ng/ml36." (PMID 29247172, 2017).
iron deficiency (continued). "After correcting ferritin concentration for inflammation (CRP) using the regression method, the prevalence of iron deficiency (ferritin <12 μg/L) was 21.4 % (415/1943) at baseline." (PMID 27391972, 2016). "Our study showed a positive correlation between ferritin and CRP, signifying an underlying low grade inflammation, leading to subsequent iron deficiency, most probably, because of inflammation mediated iron sequestration in the reticuloendothelial system." (PMID 28116148, 2016). "Iron deficiency in this study was defined by low ferritin (<30 ng/mL) in individuals with low C-reactive protein (CRP)." (PMID 24910614, 2014). "Iron deficiency (based on ferritin and C-reactive protein) was associated with lower odds for malaria infection (summary Odds Ratio = 0.35, 0.24–0.51, I2 = 59.2%, 5 studies)." (PMID 24551064, 2014). "Pooled analyses of iron deficiency status, using a definition based on ferritin and adjusting for inflammation with CRP, indicated pregnant women with iron deficiency had a reduced risk of malaria infection during pregnancy." (PMID 24551064, 2014). "Bone marrow iron deficiency, inflammation (CRP>40.0 mg/L) and high levels of erythropoietin (epo>1000 u/L), were found in 30.2%, 81.2% and 95.6% of severely anemic children, respectively." (PMID 24339866, 2013). "Other associated correlates were iron deficiency (2.1; 1.4–3.0), vitamin B12 (1.4; 1.0–2.2), and folate (2.0; 1.3–3.1) deficiencies, and C-reactive protein concentrations (>5 mg/L, 1.5; 1.1–2.2)." (PMID 22574149, 2012). "Children with functional iron deficiency had increased mean levels of CRP (126.7 (SD 85.6) mg/l) compared to those with iron stores deficiency (71.9 (SD 74.7) mg/l, p<0.001), or normal iron status (99.8 (SD 70.1) mg/l, p = 0.01)." (PMID 19638538, 2009). "Ferritin, sTfR and CRP were determined for normal iron and iron deficiency states classified by Gale’s grading method." (PMID 19638538, 2009). "Most participants (87%) also had at least one recent blood test that could be used to determine the presence of inflammation (such as C reactive protein) or iron-deficiency anaemia (such as ferritin), with 29% having at least one abnormal result." (PMID 40046831, 2025). "Traditional reliance on unadjusted ferritin may delay diagnosis of iron deficiency, particularly in patients with BMI > 30 kg/m2 and elevated CRP." (PMID 40968580, 2025). "Therefore future studies should consider assessing CRP to help differentiate between true and functional iron deficiency due to inflammation." (PMID 40677478, 2025). "Incorporating inflammatory markers like CRP or interleukin-6 (IL-6) could provide a more accurate assessment of iron status by distinguishing between inflammation-induced and true iron deficiency." (PMID 40035857, 2025). "AST, aspartate aminotransferase; BMI, body mass index; BP, blood pressure; CRP, C-reactive protein; eGFR, estimated glomerular filtration rate; ID, iron deficiency; RBC, red blood cell; TIBC, total iron-binding capacity; UIBC, unsaturated iron-binding capacity." (PMID 40481296, 2025). "Likewise, ferritin level is an important factor when stratified with age, sex, CRP, and other inflammatory markers in determining the magnitude and distribution of iron deficiency and iron overload as a public health problem." (PMID 40577412, 2025). "Moreover, magnesium deficiency is associated with inflammatory responses mediated by calcium, N-methyl-D-aspartate, and tumor necrosis factor-alpha, as well as increases in C-reactive protein (CRP)." (PMID 41019555, 2025). "It is notable that magnesium deficiency decreases both extracellular and intracellular magnesium, leading to higher calcium influx and increased cytokine release, increased oxidative stress, and an increase in C-reactive protein." (PMID 39051301, 2024). "To examine the association between BMI and iron deficiency, we used serum ferritin and CRP." (PMID 37630825, 2023).
iron deficiency (continued). "However, our study provided a comprehensive approach to BIA measurements together with nutritional and inflammatory markers such as s-albumin, and s-CRP as recognized risk indicators for nutritional disorders in dialysis." (PMID 38140295, 2023). "In addition, patients with functional iron deficiency had significantly higher CRP, IL-6, and PCT concentrations when compared to patients with absolute iron deficiency or no iron deficiency." (PMID 34658642, 2021). "Increased levels of ferritin, due to inflammation may overestimate iron status, and that is why the ferritin cut-off value for iron deficiency is increased when CRP is increased." (PMID 34066577, 2021). "Considering that CRP was elevated in almost half (45.0%) of the women, and a significant association was found between elevated CRP and ferritin levels, prevalence of iron deficiency could thus be underestimated." (PMID 33101717, 2020). "Our study revealed that higher concentrations of markers of systemic inflammation (AGP and CRP) and higher concentrations of sTfR (indicative of iron deficiency and/or increased erythropoiesis) were associated with decreased GWG per week and increased odds of low GWG." (PMID 31568674, 2020). "Iron deficiency was defined as plasma ferritin <30 μg/L if C-reactive protein (CRP) was <3 mg/L." (PMID 32541236, 2020). "Moreover, the sTfR/log ferritin cut-offs for iron deficiency differed depending on CRP concentration." (PMID 32397525, 2020). "However, for the exclusion approach, the greatest absolute change in the estimated prevalence of iron deficiency in subjects with CRP ≤ 5 mg/L was observed in pregnant women from Kisumu." (PMID 30781529, 2019). "Thus, the estimated prevalence of iron deficiency in Kisumu increased from 52.8% (all women) to 66.4% (excluding cases with Plasmodium infection, with adjustment for CRP and AGP), whilst the prevalence estimate in Nairobi increased from 29.9% to 34.6%." (PMID 30781529, 2019). "Moreover, we studied differences in expression of markers in these panels between COPD patients stratified by either iron deficiency, or the systemic inflammation marker C-reactive protein (CRP) plasma levels." (PMID 30302028, 2018). "Age, marital status, family poverty income ratio, education, health insurance coverage, daily macronutrient intake, high CRP, iron deficiency, physical inactivity, inappropriate sleeping duration, smoking, hospitalization history and history of osteoporosis were associated with frailty in males." (PMID 29507821, 2018). "The iron deficiency and the C-reactive protein up-expressions were attributed to muscle injury." (PMID 28914813, 2017). "On the other hand, regarding the importance of iron deficiency on growth and development, further investigations indicating transferrin receptor, zinc protoporphyrin, CRP along with frerritin may be more useful to address exact prevalence of IDA." (PMID 26985355, 2015). "In patients with malaria, we defined iron deficiency as plasma ferritin<30μg/ml if plasma C-reactive protein (CRP) was<50mg/ml or ferritin<273μg/ml if CRP≥50mg/ml, and in those without malaria, as ferritin<12μg/ml if CRP<10mg/ml or ferritin<30μg/ml if CRP≥10mg/ml." (PMID 21103365, 2010). "Serum ferritin, CRP, transferrin saturation, and serum iron concentration should be tested to determine the presence of iron deficiency, whereas hemoglobin blood concentration, blood count, and other micronutrients should be assessed to diagnose iron deficiency anemia." (PMID 37111210, 2023). "Thus, the estimated prevalence of iron deficiency in Kisumu increased from 52.8% (all women) to 86.7% (excluding cases with Plasmodium infection and censored CRP data, with adjustment for CRP and AGP), whilst the prevalence estimate in Nairobi increased from 29.9% to 41.3%." (PMID 30781529, 2019).